OR10H5 (olfactory receptor family 10 subfamily H member 5)
Description:
Odorant receptor.
Synonyms: OR19-25; OR19-26
Tractability: Antibody: its Gene Ontology location is reachable by antibodies, with high confidence; UniProt places it where antibodies can reach, with medium confidence; UniProt predicts a signal peptide or a membrane-spanning region.
Gene: Protein-coding gene on chromosome 19 (15,787,661 to 15,800,357, forward strand). Ensembl gene ENSG00000172519.
Subcellular location: Cell membrane
Pathways (Reactome):
Sensory Perception: Expression and translocation of olfactory receptors; Olfactory Signaling Pathway
Gene Ontology:
Molecular function: olfactory receptor activity; G protein-coupled receptor activity
Biological process: detection of chemical stimulus involved in sensory perception of smell; G protein-coupled receptor signaling pathway
Cellular component: plasma membrane; membrane
Genetic constraint (gnomAD): Loss-of-function variants: 7 observed, 12.98 expected, observed/expected ratio (o/e) 0.54, 90% interval 0.31 to 1.01. The upper end of that interval is the gene's LOEUF score, 1.01, which puts it in group 4 of 6, group 1 being the genes least tolerant of losing a copy. Missense variants: 346 observed, 414.98 expected, observed/expected ratio (o/e) 0.83, 90% interval 0.76 to 0.91. Synonymous variants: 159 observed, 173.54 expected, observed/expected ratio (o/e) 0.92, 90% interval 0.8 to 1.04.
Homologues: Orthologues: macaque OR10H5 (93% identical), mouse Or10h5 (85% identical), mouse Or10h1 (84% identical), rat Olr1092 (84% identical), rat Olr1093 (84% identical), rat Or10h1 (84% identical), mouse Or10h1b (84% identical), rat Or10h1d (83% identical), rat Olr1090 (83% identical). Paralogues in human: OR10H1 (93% identical), OR10H2 (87% identical), OR10A5 (48% identical), OR2K2 (47% identical), OR10C1 (45% identical), OR10A7 (45% identical), OR10A2 (45% identical), OR10A3 (45% identical), OR10AG1 (44% identical), OR13D1 (44% identical), OR2S2 (44% identical), OR10A4 (44% identical), and 80 more.
Diseases named in the same sentence as OR10H5 in open-access papers:
OR10H5 is named in the same sentence as 1 disease in open-access papers, as found by Europe PMC text mining. Sharing a sentence is not in itself a finding about the gene and the disease.
OR10H5 shares sentences with these, for which no sentence is quoted: colorectal cancer (1 paper).